BRCA1 (BRCA1 DNA repair associated)
Diseases named in the same sentence as BRCA1 in open-access papers (continued):
Sharing a sentence is not in itself a finding about the gene and the disease.
breast cancer (continued). "Hypoxia-inducible-factor 1 (HIF-1) alpha which is a major regulator of bioenergetics was more frequently overexpressed in BRCA1-mutated breast cancers." (PMID 40863152, 2025). "Poly (ADP-ribose) polymerase (PARP) inhibitors have emerged as a promising therapeutic strategy in the treatment of breast cancer, particularly for patients with hereditary BRCA1 and BRCA2 mutations." (PMID 40141415, 2025). "Materials and Methods: We conducted global transcriptome sequencing of breast cancer tissue samples to identify differentially expressed genes and signaling pathways associated with monoallelic somatic BRCA1 inactivation." (PMID 40870889, 2025). "It is established that mutations in BRCA1 are preferentially associated with an increased predisposition to develop a specific subtype of breast cancer, basal-like tumors." (PMID 41347767, 2025). "Another study indicated that the estimated lifetime breast cancer risk for BRCA1 and BRCA2 PV carriers increased with higher PRS313 scores, though the observed effect was smaller than in the general population or among carriers of PVs in ATM, CHEK2, and PALB2." (PMID 40296163, 2025). "Currently, PARP inhibitors are approved for use in BRCA1/2-mutated breast cancers, but their role beyond this indication is under active investigation." (PMID 40373794, 2025). "BRCA1 is a key gene involved in DNA repair 13 and its deletion is implicated in hereditary breast cancer." (PMID 41208884, 2025). "In this cohort study of 143 patients with MpBC who underwent clinical germline genetic testing, 24 (16.8%) had a PGV in a breast cancer susceptibility gene, most commonly in BRCA1." (PMID 39964682, 2025). "In 47 patients with the highest BRCA1 methylation and decreased BRCA1 expression, Sanger sequencing was performed encompassing 643 bp of BRCA1 promoter to identify potential variants associated with methylation and/or breast cancer." (PMID 40495194, 2025). "For example, in Ashkenazi Jewish (AJ) population, three BRCA1/2 (BRCA) pathogenic variants (PVs) with founder effect are responsible for 10% of breast cancers (BC) and 40% of ovarian cancers (OC)." (PMID 40563557, 2025). "BRCA1-associated breast cancers are well categorized as “BRCAness”, which lacks ER/PR/HER2, high-grade, and basal phenotypes." (PMID 41155174, 2025). "A classic example is the selective efficacy of PARP inhibitors in tumors harboring BRCA1/2 mutations, which has significantly advanced therapeutic strategies for ovarian and breast cancers." (PMID 41019981, 2025). "In a recent study, the BRCA1-∆11q splice variant, missing most exon 11, which contains an inactivating mutation of the BRCA1 gene, has been attributed to acquired resistance to PARPi, partly diminishing the sensitivity to PARPi and cisplatin in breast cancer." (PMID 40282556, 2025). "The MRI imaging features of breast cancers in women with PHTS were largely consistent with those seen in young women at average risk but differed from breast cancers in BRCA1/2 carriers and particularly from those associated with BRCA1 variants." (PMID 40075703, 2025). "Around 10–15% of breast cancer cases in young women are diagnosed in patients with germline pathogenic or likely pathogenic variants in the BRCA1 or BRCA2 genes." (PMID 41077566, 2025). "Research findings suggest that U. dioica extract modulates key molecular pathways associated with obesity and breast cancer, leading to the downregulation of critical markers like Dgat1, Lpl, Fas, Mcp1, Brca1, and Brca2 in LPS induced adipocytes." (PMID 40153121, 2025). "Significant research has focused on breast cancer imaging features in breast MRI and mammography in women with BRCA1/2 pathogenic variants, as well as in the general population." (PMID 40075703, 2025).
breast cancer (continued). "The aim of this study is to review and summarize the existing data on genetic modifiers of breast cancer risk in female BRCA1 and BRCA2 pathogenic variants carriers." (PMID 40296163, 2025). "Of 895 patients with a known pathogenic variant in BRCA1/2 and PALB2 or other breast cancer susceptibility genes, we identified 312 affected female BRCA1/2 and PALB2-positive patients with breast cancer." (PMID 40275390, 2025). "Methylation of BRCA1 has been associated with an increased risk of breast cancer and specific clinical characteristics of the disease." (PMID 40495194, 2025). "A family history of breast cancer was reported in 13.9% of patients, and BRCA1/2 mutations were confirmed in 4.2%." (PMID 40710890, 2025). "Approximately 10% of breast cancer cases are hereditary, and germline pathogenic variants (PVs) in BRCA1 account for nearly 35% of these." (PMID 41440233, 2025). "The combination of the CHK1 inhibitor, SRA737, with Adavosertib enhanced tumor growth inhibition in the BRCA1-mutated breast cancer cell line MDA-MB-436 xenograft model." (PMID 40565165, 2025). "Inherited mutation in BRCA1 gene predisposes female carriers to early onset tumorigenesis and up to 87% cumulative lifetime risk of developing breast cancer." (PMID 41318657, 2025). "PARP3 regulates TGFβ-induced cytoskeletal rearrangement, leading to formation of lamellipodia, the numbers of which are elevated in BRCA1-deficient breast cancer cells." (PMID 40741921, 2025). "Mutations of BACH1 or BRCA1 affect the DNA repair process negatively and also result in a higher risk for breast cancer." (PMID 39621070, 2025). "Both BRCA1 and −2 carriers are more likely to develop early-onset breast cancer, but the association is stronger for BRCA1mutated patients." (PMID 39955428, 2025). "HRD gained prominence with the discovery that mutations in the breast cancer genes BRCA1 (Breast Cancer Gene 1) or BRCA2 (Breast Cancer Gene 2) impair HRR." (PMID 40864792, 2025). "Based on this value, family history-positive individuals contributed 25.55% of BRCA1/2 mutations, aligning reasonably with breast cancer data." (PMID 40567951, 2025). "For instance, the loss-of-function mutation of BRCA1 is a well-known cause of breast cancer cell genome instability." (PMID 40003882, 2025). "The results suggested that BRCA1/2 mutations were associated with breast cancer that exhibited more aggressive behavior, particularly in younger age groups." (PMID 41463058, 2025). "When compared to sporadic breast carcinomas and the BRCA2 DNA repair associated (BRCA2) mutant tumors, basal-like breast cancers and tumors arising in carriers of the BRCA1 germ-line mutation exhibit a peculiar pattern of cell cycle protein expression." (PMID 40141415, 2025). "Screening programs for BRCA1/2 P/LP variant carriers typically involve a combination of annual MRI and mammography to enhance early detection of breast cancer." (PMID 40834323, 2025). "BRCA1 deficiency induces ferroptosis vulnerability to PARP and GPX4 co-inhibition, which is useful for therapeutic strategies to overcome PARP inhibitor resistance in BRCA1-deficient cancers, including breast cancer." (PMID 39858464, 2025). "Among cancer, 30% aimed to enhance breast cancer screening programmes, including magnetic resonance imaging for high-risk individuals with BRCA1/2 mutations or other associated genetic variants." (PMID 39804869, 2025). "Non-modifiable factors include female sex, older age, a positive family history of breast cancer and the presence of BRCA1 or BRCA2 mutations." (PMID 40940924, 2025). "The few studies investigating the difference in magnitude of the association between OC use and breast cancer risk depending on genetic predisposition have primarily focused on carriers of the BRCA1 and BRCA2 mutations." (PMID 41327462, 2025). "Chemotherapy receipt was 80.6% in BRCA1-associated breast cancers compared to 56.9% in BRCA2 and 84.2% in PALB2 associated breast cancers (p < 0.001)." (PMID 40275390, 2025).
breast cancer (continued). "Robust clinical trials demonstrated the efficacy and safety of the poly (ADP-ribose) polymerase inhibitors (PARPis) in patients with HER2-negative advanced breast cancer and pathogenic germline BRCA1/2 mutations (gBRCAm)." (PMID 40361341, 2025). "Further, research has highlighted the connection between elevated progesterone levels and upregulation of the RANK pathway, with implications for breast cancer development in women with BRCA1 mutations." (PMID 39941709, 2025). "OPG, a decoy receptor for RANKL, is found at lower levels in BRCA1 mutation carriers, suggesting its potential as a biomarker for breast cancer risk." (PMID 39941709, 2025). "For instance, within the eRNA‐TWAS‐identified breast cancer susceptibility eRNA‐linked genes, two widely recognized breast cancer susceptibility genes, BRCA1 and FGFR2, were found to have statistically significant associations (FDR < 0.05)." (PMID 39950845, 2025). "Concerns regarding the potential impact of these interventions on breast cancer risk, particularly among high-risk women with a pathogenic variant in the BRCA1 or BRCA2 genes remains an important clinical concern." (PMID 41214587, 2025). "The cumulative risk of developing breast cancer at age 70 is 51–75% with a median age of onset of 40 years for patients with the BRCA1 mutation, and 33–55% with a median age of onset of 43 years for patients with the BRCA2 mutation." (PMID 40142718, 2025). "Approximately 10% of breast cancer is inherited; women with deleterious germline BRCA1 or BRCA2 mutations have a lifetime 60–70% risk of breast cancer." (PMID 41350536, 2025). "Most breast cancer susceptibility genes are involved in the damage repair signaling pathway, i.e., including BRCA1, BRCA2, PALB2, CHEK2, ATM, BARD1, RAD51C, and RAD51D." (PMID 40649769, 2025). "For example, studies focusing on breast cancer patients and their families estimated the penetrance of BRCA1 and BRCA2 mutations by age 70 to be 65–85% and 70–84%, respectively." (PMID 39858629, 2025). "Still, they also contribute significantly to the pathogenesis of breast cancer, particularly in BRCA1 mutation carriers." (PMID 40243654, 2025). "The presence of pathogenic mutations in the BRCA1 tumor suppressor gene increases the risk of developing a number of oncological diseases including breast cancer (up to 70%)." (PMID 40429927, 2025). "A randomized, double-blind, phase III clinical trial (NCT02849496) demonstrated that adding olaparib to neoadjuvant or adjuvant chemotherapy significantly improved IDFS in patients with early-stage HER2- breast cancer who also had a BRCA1 or BRCA2 mutation." (PMID 40134916, 2025). "Genetic testing data revealed frequent BRCA1/2 testing, underscoring its importance in assessing breast cancer risk." (PMID 40941615, 2025). "The main point of BRCA1 mutations is relevant to both diseases and strategies for preventing breast cancer." (PMID 40385922, 2025). "Background/Objectives: PARP inhibitors (PARPi) are pivotal to treating homologous recombination repair-deficient (HRD) cancers, particularly BRCA1/2-mutated ovarian and breast cancers." (PMID 40299557, 2025). "Pathogenic germline mutations of BRCA1/2 genes are the most common hereditary cause of breast cancer and ovarian cancer." (PMID 40371388, 2025). "Its potential to prevent breast cancer in high-risk BRCA1 mutation carriers when administered biannually for five years is under investigation (NCT04711109)." (PMID 40243654, 2025). "The most common heritable mutations associated with increased breast cancer risk are those in the BRCA1 and BRCA2 genes." (PMID 40390103, 2025).
breast cancer (continued). "Breast cancer patients with a heterozygous pathogenic BRCA1 germline variant appear to have significantly higher hematotoxicity than patients without the corresponding mutation." (PMID 40519304, 2025). "Third, subsequent research should investigate the potential of DL models for classifying molecular subtypes of breast cancer and for accurately characterizing BRCA1/2 mutation status." (PMID 41049432, 2025). "For PALB2 P/LP variant carriers, the surveillance for breast cancer should be equivalent to that for BRCA1 and BRCA2 P/LP variant carriers." (PMID 39858629, 2025). "RAPTA derivatives have been shown to be significantly more effective against BRCA1-deficient breast cancer cells than cisplatin." (PMID 41155174, 2025). "İn this context, recent evidence on trace element homeostasis has shown an association with breast cancer development in BRCA1 mutation carriers." (PMID 41010899, 2025). "Among the breast cancer subgroups, patients with BRCA1/2 mutation exhibited significantly lower baseline levels of resolvin D1 compared to other subgroups." (PMID 40427191, 2025). "The OCCR refers to regions within BRCA1/2 associated with a higher risk of ovarian cancer compared to breast cancer." (PMID 40075604, 2025). "Loss of BRCA1 is associated with the onset of breast cancer and alterations in the immune system within breast tissue are considered to play an important role in this process." (PMID 41208884, 2025). "The cumulative lifetime risk of breast cancer is estimated at 72% (95% confidence interval [CI], 65%–79%) for BRCA1 carriers and 69% (95% CI, 61%–77%) for BRCA2 carriers by the age of 80." (PMID 41083355, 2025). "A similar calculation for breast cancer was conducted by using BRCA1/2 as high-risk genes and CHEK2, ATM and PALB2 for intermediary risk genes." (PMID 40016794, 2025). "Signatures of somatic mutations have been identified in HR deficient BRCA1/2-associated breast cancer and BRCA2-mutated prostate cancers." (PMID 40437549, 2025). "In contrast, HER2-negative breast cancer (BC) patients showed a numerically higher rate of pCR in BRCA1 vs. BRCA2 mutation carriers [38/69 (55%) vs. 13/36 (36%), P = 0.1]." (PMID 40547808, 2025). "Breast cancer (BC) is the most common cancer affecting women, with up to 10% of cases attributed to hereditary gene predispositions, such as BRCA1 and BRCA2 mutations." (PMID 40422528, 2025). "Approximately 10% of BC cases harbor a germline mutation in the breast cancer genes 1 (BRCA1) or 2 (BRCA2), (gBRCAm), which affects the homologous repair mechanism of DNA double-strand breaks." (PMID 40805203, 2025). "The association of screening mammography with breast cancer (BC) was investigated in cases with a hereditary predisposition unexplained by BRCA1 or BRCA2 and unrelated controls." (PMID 40227588, 2025). "Women with germline pathogenic variants in BRCA1 or BRCA2 (BRCA1/2 carriers) have about a 70% lifetime risk of developing breast cancer (BC)." (PMID 40728683, 2025). "Women with germline pathogenic variants (PVs) in BRCA1 or BRCA2 genes have a significantly increased lifetime risk for breast cancer (BC) compared with the general population." (PMID 40042736, 2025). "Current genetic screening for predisposition to breast cancer (BC) is limited to BRCA1/2 exons and intron/exon boundaries, and limited information exists about the impact of variants in BRCA1/2 non-coding regions." (PMID 40338220, 2025). "A retrospective cohort of 75 breast cancer patients with known BRCA1/2 mutation status, who were diagnosed with CNS metastases in 2006–2021." (PMID 38365640, 2024).
breast cancer (continued). "While the risk of contralateral breast cancer in BRCA1 mutation careers decreases after menopause, incidence increases in BRCA2 mutation carriers." (PMID 38059556, 2024). "A significant retrospective study from the Breast Cancer Linkage Consortium revealed an elevated chance of uterine cancer for BRCA1 mutation carriers, but weren’t for BRCA2 mutation carriers (RR = 2.65; 95% CI: [1.69,4.16]; P < 0.001)." (PMID 38297203, 2024). "The results of this suggest a potential for reduction in breast cancer risk in BRCA1 carriers using iodine but should only be considered after preventive oophorectomy." (PMID 38892720, 2024). "Although, the RING-domain is associated with a lower OC risk compared to breast cancer, still one germline and six somatic BRCA1 variants were detected in this region." (PMID 38519644, 2024). "Individuals harboring breast cancer gene 1/2 (BRCA1/2) pathogenic variants are at increased lifetime risk for developing cancer." (PMID 39050256, 2024). "One year of adjuvant olaparib is currently indicated either alone or concurrently with endocrine therapy in early breast cancer with BRCA1- or BRCA2-mutated high-risk patients that have received local treatment and neoadjuvant or adjuvant chemotherapy." (PMID 38869741, 2024). "In tumour cells lacking HR proficiency, PARG inhibition appears to cause synthetic lethality, in a similar vein to the archetypal synthetic lethality of PARP inhibitors in BRCA1/2-deficient breast cancer cells." (PMID 38368415, 2024). "One particularly noteworthy factor in hereditary breast cancer is the presence of pathogenic variants in the breast cancer susceptibility genes BRCA1 and BRCA2." (PMID 38167124, 2024). "Prexasertib has showed moderate clinical efficacy in a phase 2 trial on BRCA1/2-mutated breast cancer and sporadic TNBC is ongoing; 1 of 9 patients reached PR and 4 of 9 attained stable disease." (PMID 39334297, 2024). "We used Blg-Cre; Brca1F/F; Trp53F/F mice, a model that phenocopies human basal-like breast cancer with BRCA1 mutations." (PMID 38835038, 2024). "This is because BRCA1 PV-associated breast cancers, most of which are hereditary, predispose patients to triple-negative and basal-like cancers." (PMID 39682099, 2024). "The ERα gene and BRCA1 gene, which are strongly associated with breast cancer, have been observed in epigenetic programming." (PMID 38803501, 2024). "In summary, our study revealed that WWOX and BRCA1 loss led to the development of basal-like mammary tumors and impaired DSB repair." (PMID 38499540, 2024). "Downstream mediators linked to LYN activation of NFκB include MEK, IKKα (or CHUK), PI3K, MAPK and IκB, and there is also support for a role of NFκB activation in BRCA1 loss-of-function-associated breast cancers." (PMID 38149669, 2024). "Two human BRCA1-mutated breast cancer cell lines and their isogenic BRCA1-recovered pairs were treated with a PARP inhibitor and irradiated with photons or protons." (PMID 39730675, 2024). "Functionally, BRCA1 is involved in the Breast Cancer Susceptibility Protein-Associated Genome Surveillance Complex (BASC) and plays a key role in detecting and repairing DNA damage by interacting with proteins such as Rad51." (PMID 38543119, 2024). "The aberrant amplification of mammary luminal progenitors is at the origin of basal-like breast cancers associated with BRCA1 mutations." (PMID 38835038, 2024). "Traditionally, the BRCA1/2 genes in the HRR pathway have been tested for their association with breast cancer." (PMID 38397152, 2024). "Q1: Predictive genetic tests for BRCA1/2 mutations are able to identify patients at high risk of developing breast cancer." (PMID 39446329, 2024).